LDLRAD2 (low density lipoprotein receptor class A domain containing 2)
Tractability: Antibody: UniProt predicts a signal peptide or a membrane-spanning region.
Gene: Protein-coding gene on chromosome 1 (21,812,265 to 21,825,225, forward strand). Ensembl gene ENSG00000187942.
Subcellular location: Membrane
Gene Ontology:
Cellular component: membrane
Genetic constraint (gnomAD): Loss-of-function variants: 26 observed, 24.7 expected, observed/expected ratio (o/e) 1.05, 90% interval 0.77 to 1.46. The upper end of that interval is the gene's LOEUF score, 1.46, which puts it in group 6 of 6, group 1 being the genes least tolerant of losing a copy. Missense variants: 391 observed, 360.67 expected, observed/expected ratio (o/e) 1.08, 90% interval 1 to 1.18. Synonymous variants: 182 observed, 161.33 expected, observed/expected ratio (o/e) 1.13, 90% interval 1 to 1.28.
Homologues: Orthologues: chimpanzee LDLRAD2 (97% identical), macaque LDLRAD2 (93% identical), pig LDLRAD2 (78% identical), rabbit LDLRAD2 (77% identical), dog LDLRAD2 (76% identical), rat Ldlrad2 (65% identical), mouse Ldlrad2 (63% identical), tropical clawed frog ldlrad2 (46% identical), zebrafish ldlrad2 (45% identical). Paralogues in human: CD320 (16% identical).
Diseases named in the same sentence as LDLRAD2 in open-access papers:
LDLRAD2 is named in the same sentence as 4 diseases in open-access papers, as found by Europe PMC text mining. Sharing a sentence is not in itself a finding about the gene and the disease. The quoted sentences say what the papers report.
gastric cancer (1 paper, 2019). A primary or metastatic malignant neoplasm involving the stomach. "The relationship between LDLRAD2 expression and clinicopathological features of patients with gastric cancer." (PMID 31649207, 2019).
pancreatic cancer (1 paper, 2024). "LDLRAD2 is a gene involved in various human diseases, particularly common in pancreatic cancer cell lines and tissues." (PMID 39349424, 2024). "It is known that low-density lipoprotein receptor class A domain-containing 2 (LDLRAD2) plays a significant role in the progression of pancreatic cancer." (PMID 39349424, 2024). "Knocking out LDLRAD2 successfully decreases the proliferation, invasion, and metastasis of pancreatic cancer cells." (PMID 39349424, 2024). "Therefore, it has been confirmed that LDLRAD2 is involved in the progression of pancreatic cancer by regulating the AKT/mTOR pathway." (PMID 39349424, 2024).
tumor (1 paper, 2019). "In summary, our findings demonstrate that high LDLRAD2 expression strongly correlates tumor aggressiveness and poor prognosis, and LDLRAD2 activates Wnt/β-catenin pathway by interacting with Axin1 to EMT, invasion and metastasis of GC cells." (PMID 31649207, 2019). "Consistently, the results of immunohistochemical staining also showed that LDLRAD2 expression was highly expressed in tumor tissues." (PMID 31649207, 2019). "Firstly, we determined whether LDLRAD2 expression has an effect on EMT, considering the role of epithelial-mesenchymal transition (EMT) in tumor invasion." (PMID 31649207, 2019).
LDLRAD2 also shares sentences with these, for which no sentence is quoted: acute myeloid leukemia (1 paper).